MT2A (metallothionein 2A)
Diseases named in the same sentence as MT2A in open-access papers (continued):
Sharing a sentence is not in itself a finding about the gene and the disease.
bladder cancer (continued). "Furthermore, MT2A overexpression in bladder cancer cell lines significantly downregulated endogenous ROS production and alleviated H2O2-induced ROS, further confirming MT’s antioxidative properties." (PMID 39959428, 2025). "We continued to determine the antioxidant response of MT2A in human bladder carcinoma cells." (PMID 36009228, 2022). "Thus, it is warranted to determine whether MT2A could control ROS through regulating HO-1 in bladder carcinoma cells." (PMID 36009228, 2022). "However, the antioxidative effect of MT2A in bladder carcinoma cells is yet to be determined." (PMID 36009228, 2022). "Similar results were presented in bladder carcinoma HT1376 cells, in which CAPE treatment upregulated MT2A and HO-1 expressions and MT2A knockdown attenuated the activation of CAPE on HO-1 protein levels." (PMID 36009228, 2022). "Unlike bladder cancer tissues, the real-time reverse transcriptase-polymerase chain reaction (RT-qPCR) analysis showed a significant level of MT2A mRNA in the normal bladder tissues." (PMID 36009228, 2022). "Nevertheless, the biological activity of CAPE on the expression of MT2A in bladder cancer has not yet been investigated." (PMID 36009228, 2022). "Functions of metallothionein 2A (MT2A) in bladder cancer have not been extensively explored even though metallothioneins are regarded as modulators in several biological regulations including oxidation and cancerous development." (PMID 36009228, 2022). "The results of the present study indicated that knockdown of MT2A significantly resisted H2O2 treatment-induced cell apoptosis, while ectopic overexpression of MT2A significantly enhanced cell apoptosis induced by H2O2 in bladder carcinoma cells." (PMID 36009228, 2022).
esophageal squamous cell carcinoma (3 papers, 2021 to 2022). Esophageal squamous cell carcinoma (ESCC) is a type of esophageal carcinoma (EC) that can affect any part of the esophagus, but is usually located in the upper or middle third. "However, MT2A is highly expressed in esophageal squamous cell carcinoma (ESCC) cells and promotes ESCC cell migration and invasion by regulating the expression and secretion of IGFBP2, thus influencing the NFκB, Akt and Erk signaling pathways." (PMID 35642057, 2022). "Therefore, MT2A, MT1E, MT1X may be potential predictors of anti-PD-1 therapy in patients with advanced esophageal squamous cell carcinoma." (PMID 36466860, 2022).
lung adenocarcinoma (3 papers, 2022 to 2025). A carcinoma that arises from the lung and is characterized by the presence of malignant glandular epithelial cells. "A recent study has found that high expression of MT2A is associated with poor prognosis of lung adenocarcinoma." (PMID 35642057, 2022). "High expression of MT2A is associated with poor prognosis of lung adenocarcinoma." (PMID 39495117, 2024). "To determine the clinical relevance of the Hippo-MTF1 pathway, we analyzed data from The Cancer Genome Atlas (TCGA) regarding the expression of MTF1 and its downstream genes MT1A and MT2A in lung adenocarcinoma (LUAD) cancer patients." (PMID 39920630, 2025).
melanoma (3 papers, 2016 to 2024). A malignant, usually aggressive tumor composed of atypical, neoplastic melanocytes. "MT2A and other family members were shown to be overexpressed in melanoma and were associated with increased macrophage density of TME." (PMID 35269844, 2022). "Using an in silico cohort of IFN-treated melanoma tissues, we validated a differentially expressed 9-gene core of DEGs, out of which four genes had a predictive power for efficacy: WFDC1, HSPB7, HSF1, and MT2A." (PMID 35269844, 2022). "Thus, while known targets of CPEB4 such as the metallothionein proteins MT2A and MT1E were found in both cell types, 93% of the CPEB4-bound transcripts in melanoma (that is, 312/331) had not been reported in RWP1." (PMID 27857118, 2016).
Hyperglycemia (2 papers, 2021 to 2023). An increased concentration of glucose in the blood. "Thus, in comparison to control FVB mice, transgenic mice overexpressing the human MT2A gene under the control of the human insulin promoter (MT2A-Tg) exhibited reduced hyperglycemia after STZ injection." (PMID 33652748, 2021).
laryngeal carcinoma (2 papers, 2015 to 2016). Carcinoma that arises from the laryngeal epithelium. "Unfortunately, as a literature survey revealed no publication describing a genetic implication of MT2A SNPs in the pathogenesis of head and neck tumors, the harvested results can only be compared to our previous reports in laryngeal cancer." (PMID 26036762, 2015).
lymphoma (2 papers, 2022 to 2024). A malignant (clonal) proliferation of B- lymphocytes or T- lymphocytes which involves the lymph nodes, bone marrow and/or extranodal sites. "Moreover, an early study has indicated that MT2A and HO-1 are increased along with the stimulation of gallium nitrate in human lymphoma cells." (PMID 36009228, 2022). "Interestingly, our data suggested that Mt2 might be a male-specific negative prognostic factor in murine Eμ-Myc-induced lymphomas, but MT2A expression levels had no prognostic value in human lymphomas." (PMID 39298333, 2024).
pancreatic cancer (2 papers, 2023 to 2025). "Although LIPE, MT2A, PLD4 and ZNF589 have been studied in other tumours, their relationship with tumour-associated macrophages in pancreatic cancer remains to be investigated." (PMID 37469705, 2023). "However, ABCB4, ENPP6, FGFBP2, MT2A, OXER1, PLD4 and ZNF589 were low expressed in pancreatic cancer tissues." (PMID 37469705, 2023).
periodontal disease (2 papers, 2019 to 2022). "The present validation study confirmed that the genes for the MT1F, MT1X, MT1M, MT1E, and MT2A isoforms exhibit a statistically significant alteration of expression in Down’s syndrome patients with active periodontal disease and implant failure." (PMID 35741790, 2022).
psychosis (2 papers, 2008 to 2023). "In the current cross-study analysis, we identified a set of metallothionein genes including MT1X, MT1K, MT1E, MT1H, MT1F, MT2A and MT3 that are significantly up-regulated in psychosis." (PMID 18992145, 2008). "Using a quantitative PCR, we validated a set of genes such as up-regulated metallothioneins (MT1E, MT1F, MT1H, MT1K, MT1X, MT2A and MT3) and down-regulated neuropeptides (SST, TAC1 and NPY) in the dorsolateral prefrontal cortex of psychosis patients." (PMID 18992145, 2008). "In a study conducted on postmortem subjects with and without psychosis, up-regulation in MT1E, MT1F, MT1H, MT1K, MT1X, MT2A, and MT3 genes was observed in the dorsolateral prefrontal cortex." (PMID 36831126, 2023).
retinal degeneration (2 papers, 2021). Degeneration of the retina. "Mt2A, which encodes metallothionein 2A protein, protecting against hydroxyl free radicals and metal iron toxicity, preserved from various forms of retinal degeneration." (PMID 33537951, 2021).
schizophrenia (2 papers, 2008 to 2017). A major psychotic disorder characterized by abnormalities in the perception or expression of reality. "Similar to our findings, one study reported that MT2A gene expression is increased in the PFC of schizophrenia patients." (PMID 18992145, 2008). "The paralogous genes of GBP1, MT2A and APOL1, including GBP2, MT1G, MT1E, MT1F, MT1L and APOLD1, were also upregulated in the schizophrenia cases." (PMID 28809853, 2017).
scrapie (2 papers, 2011 to 2013). A fatal disease of the nervous system in sheep and goats, characterized by pruritus, debility, and locomotor incoordination. "In accordance with this finding, we observed a significant overexpression of the metallothionein 2A (MT2A) gene in scrapie medullae, which was positively associated with prion deposition but not with GFAP immunostaining." (PMID 21629698, 2011). "The increased expression of CAPN6, GALA1 and MT2A in most of the brain regions analyzed suggests a potential role of these genes in early and terminal scrapie pathogenesis, which is further supported by immunohistochemical and immunoblotting evidence." (PMID 23497022, 2013). "In addition to the overexpression previously reported for MT2A in the medulla oblongata during clinical scrapie, a significant over expression of MT2A was observed in the four CNS regions analyzed in clinical scrapie and in the cSc and Cc of the preclinical scrapie-infected animals." (PMID 23497022, 2013). "The gene and protein expression profiles and protein distribution of six potential genetic biomarkers (i.e., CAPN6, COL1A2, COL3A1, GALA1, MT2A and MTNR1B) are presented here for both the early and terminal stages of scrapie in five different brain regions." (PMID 23497022, 2013). "The distribution of the GALA1 was identified in glial cells from the cerebellum of scrapie-infected animals, GALA1 protein expression was increased in clinical animals in the majority of regions, and the increase of MT2A was in agreement with previous reports." (PMID 23497022, 2013).
type 2 diabetes (2 papers, 2023). "Metallothionein 2a gene expression was reported to be increased in subcutaneous adipose tissue of type 2 diabetic patients." (PMID 36690679, 2023).
acute myeloid leukemia (1 paper, 2021). Acute myeloid leukemia (AML) is a group of neoplasms arising from precursor cells committed to the myeloid cell-line differentiation. "Although accumulating evidence has revealed that metallothioneins (MTs) and its family member MT2A are strongly linked to the risk of various solid tumors, researches on the occurrence and development of acute myeloid leukemia (AML) have rarely been investigated." (PMID 34220318, 2021).
acute pancreatitis (1 paper, 2021). An acute inflammatory process that leads to necrosis of the pancreatic parenchyma. "Therefore, the aim of this study was to investigate the SNPs that may contribute to the exacerbation of inflammation, rs11640851 in the MT1A gene, rs964372 in the MT1B gene and rs10636 in the MT2A gene, in patients with acute pancreatitis (AP) and healthy subjects." (PMID 34072023, 2021).
chronic gastritis (1 paper, 2020). Inflammation of the stomach that is chronic in nature. "The down-regulation of NDUFS8 (NADH: Ubiquinone Oxidoreductase Core Subunit S8), MT2A (Metallothionein 2A), HDAC7 = Histone Deacetylase 7, and PDK1 (Pyruvate dehydrogenase kinase 1) in chronic gastritis and intestinal metaplasia, respectively, was also confirmed." (PMID 31897247, 2020).
chronic kidney disease (1 paper, 2022). Impairment of the renal function secondary to chronic kidney damage persisting for three or more months. "The study provides evidence that proteinuric chronic renal failure may increase plasma metal levels where blood MT2A could be a marker." (PMID 35735634, 2022). "Enhanced MT1A and MT2A mRNA levels in subjects with chronic kidney disease (p < 0.01) compared to NEC rather than EC, and higher metals and metalloid levels (p < 0.05) in EC compared to NEC suggest that elevated plasma burden of metals could be the reason for MT upregulation in an endemic area." (PMID 35735634, 2022).
colorectal adenocarcinoma (1 paper, 2022). The most common type of colorectal carcinoma. "Subsequently, MT2A overexpression inhibited the proliferation and metastasis of human colorectal adenocarcinoma HCT8 and HCT116 cells in vitro." (PMID 35642057, 2022). "However, other studies have shown that MT2A is upregulated in human colorectal adenocarcinoma HT29 cells, and the interaction between pFADD and MT2A inhibits the apoptosis of Colo 205 cells and induces cell proliferation." (PMID 35642057, 2022).
colorectal tumor (1 paper, 2023). "A multiple gene analysis showed that the expression levels of MT1 isoforms and MT2A were lower in metastatic tissues and colorectal tumor tissues than in normal colorectal tissue using gene chip-based data." (PMID 38068944, 2023).
COVID-19 (1 paper, 2023). A disease caused by infection with severe acute respiratory syndrome coronavirus 2. "Interestingly, we found metal ion homeostasis pathway associated with metallothionein (MT2A, MT1E, and MT1X) genes enriched within CD8+ TCM, CD8+ TEM, and activated CD4+ T cells in the COVID-19 positive individuals." (PMID 37886355, 2023). "In our data, the response to cytokine pathway also shows upregulated expression of MT2A and MT1X in the COVID-19 patients." (PMID 37886355, 2023).
diabetic nephropathy (1 paper, 2023). "Therefore, results from this study suggest that the C allele of MT2Ars10636 may be a favorable factor for diabetic patients, and that MT2A may offer a novel therapeutic target against diabetic nephropathy." (PMID 36690679, 2023).
dilatation (1 paper, 2022). "Another study has reported an increased expression of MT1A and MT2A in the myometrium of women with arrest of cervix dilatation during labour." (PMID 36103557, 2022).
endometrial cancer (1 paper, 2023). Primary or metastatic malignant neoplasm involving the endometrium (mucous membrane that lines the endometrial cavity). "Having conducted a literature review, we found no previous studies on the relationship between the polymorphisms of MT1A (rs11076161), MT2A (rs28366003) and MT1L (rs10636) and the possibility of developing endometrial cancer." (PMID 36981043, 2023). "In our study, we decided to determine the presence of MT1A (rs11076161), MT2A (rs28366003) and MT1L (rs10636) polymorphisms among the studied patients as research on the influence of the selected polymorphisms on the risk of developing endometrial cancer has not yet been conducted." (PMID 36981043, 2023).
endometriosis (1 paper, 2022). The growth of functional endometrial tissue in anatomic sites outside the uterine body. "Among the 15 DEPs, COL1A1, COL6A2, and NID2 are among the proteins with strong interactions, and MT2A, TYMP, COL1A1, and COL6A2 have already been associated with endometriosis." (PMID 36232817, 2022).
ependymoma (1 paper, 2010). A WHO grade II, slow growing tumor of children and young adults, usually located intraventricularly. "MT2A expression level did not change significantly in the ependymoma primary and in DAOY cells after TSA treatment." (PMID 20885975, 2010).
gastric tumors (1 paper, 2013). "Hence, we focused to reveal the co-expression of MT2A and IκB-α gene correlated with clinical pathological features and outcomes in a large scale of gastric tumors with long-term follow-up data." (PMID 23870553, 2013).
gestational hypertension (1 paper, 2022). "The genetic variation rs10636 G in MT2A was related to a decreased risk of gestational hypertension." (PMID 35734434, 2022).
hearing loss (1 paper, 2021). "In the present study, expression levels of MT1A and MT2A were increased in rats with KM-induced hearing loss and were normalized in KM + FM-treated rats." (PMID 34070066, 2021). "Furthermore, the expression levels of MT1A and MT2A and transmembrane megalin receptors were elevated in rats presenting KM-induced hearing loss." (PMID 34070066, 2021).
Hepatitis (1 paper, 2021). Inflammation of the liver. "In dogs with hepatitis, MT1A and MT2A expression levels decrease together with a copper concentration in hepatic cells." (PMID 33995471, 2021).
hepatoblastoma (1 paper, 2009). Hepatoblastoma (HB) is a malignant hepatic tumor and is the most common pediatric liver cancer. "Examples are genes encoding heat shock 70 kDa protein 1A (Hsp70/HspA1A) in HeLa cells, prion protein (PrP) in neurons and metallothionein 2A (MT2A) in hepatoblastoma cells." (PMID 19305496, 2009).
hyperlipidemia (1 paper, 2020). "The C allele of MT2A rs10636 was associated with hyperlipidemia." (PMID 32340109, 2020).
Hypertension (1 paper, 2014). The presence of chronic increased pressure in the systemic arterial system. "‘Unknown I’ contained a diverse set of key driver genes such as SGK1, SIK1 and SLC10A6 (sodium metabolism and hypertension), MT2A and TSC22D3 (glucocorticoid signaling), GADD45G, ERRFI1, GPRC5A, and EGFR (cell growth and apoptosis), and CEBPB, CEBPD, and KCNA5 (heart development and function)." (PMID 25033284, 2014).
inverted papilloma (1 paper, 2015). An endophytic benign papillary epithelial neoplasm that results from the invagination and proliferation of epithelial cells in the underlying stroma. "The present study documents the contribution of the −5 A/G single-nucleotide polymorphism in the MT2A gene toward the risk of developing inverted papilloma in a Polish population." (PMID 26036762, 2015). "Our study also documents the relationship between the SNPs in the MT2A gene and the dynamics of tumor growth, according to a thorough multifactorial histological evaluation of inverted papillomas." (PMID 26036762, 2015). "It should be emphasized that, at the time of writing, no publication has yet analyzed the SNPs of MT2A in relation to human inverted papilloma susceptibility." (PMID 26036762, 2015).
Iron deficiency anemia (1 paper, 2023). "As MT2Ars10636 CC subjects had significantly lower MCH and higher platelet counts, genetic variations of MT2A also deserve to be taken into consideration in iron deficiency anemia." (PMID 36690679, 2023).
leukemia (1 paper, 2021). A malignant (clonal) hematologic disorder, involving hematopoietic stem cells and characterized by the presence of primitive or atypical myeloid or lymphoid cells in the bone marrow and the blood. "Besides, compared with the control group, there was a significant increase in the number of apoptotic cells, suggesting that MT2A could induce the apoptosis rate of leukemia cells and reduce the cell survival rate, which is consistent with the results of CCK-8 and colony formation assay." (PMID 34220318, 2021).
mastitis (1 paper, 2024). Inflammation of breast tissue during lactation or postpartum due to an obstructed duct or infection. "This was followed by ACKR1, MT2A, and S100A12, which are associated with mastitis and mastitis response." (PMID 39333243, 2024).
mucoepidermoid carcinoma (1 paper, 2022). A carcinoma morphologically characterized the presence of cuboidal mucous cells, goblet-like mucous cells, squamoid cells, cystic changes, and a fibrotic stromal formation. "Similarly, MT2A depletion is associated with decreased expression of TGF-α and MMP-9, and MT2A silencing reduces the migration and invasion activities of mucoepidermoid carcinoma." (PMID 35642057, 2022).
neuroblastoma (1 paper, 2021). Neuroblastoma (NB) is the most common solid, extracranial childhood tumor. "In a previous report of our laboratory, phenotyping of MYCN-amplified Kelly and SK-N-BE-2-C neuroblastoma cell lines, a high expression variance of metallothionein genes, such as MT2A and MT1X, was already reported, especially in Kelly cells." (PMID 34066513, 2021).
nutritional deficiency (1 paper, 2022). "Paneth cell markers were also downregulated in EED chips compared with healthy chips in control medium (for example, MT2A, CFTR and MT1H were suppressed by ~2–2.5-fold, respectively), but were differentially regulated when chips were exposed to nutritional deficiency." (PMID 35739419, 2022).
oral squamous cell carcinoma (1 paper, 2024). "Dias and colleagues found that reducing metallothionein 2A levels using siRNA lowered MMP-9 and EGF protein levels, leading to decreased proliferation, migration, and invasion in human oral squamous cell carcinoma cells." (PMID 38374934, 2024).
ovarian tumors (1 paper, 2018). "MT2A is upregulated in chemotherapy resistant ovarian tumors, and also in human prostate cell lines." (PMID 29721183, 2018).
pleural mesothelioma (1 paper, 2024). A neoplasm that arises from the mesothelial cells of the pleura. "Knockdown of MT2A expression in malignant pleural mesothelioma cell lines resulted in a significant increase in apoptosis in response to cisplatin." (PMID 39061894, 2024).